CXCL12 (C-X-C motif chemokine ligand 12)
Diseases named in the same sentence as CXCL12 in open-access papers (continued):
Sharing a sentence is not in itself a finding about the gene and the disease.
tumor (continued). "The activation of CXCL12/CXCR4 might accelerate PNI through enhancing the initiation of EMT to induce tumour cells develop into Schwann‐like cells, triggering cytoskeletal rearrangement, thus acquiring a promotional migrated and invasive ability in SACC." (PMID 34170080, 2021). "CXCL12 is also secreted by BCAFs and directly promotes tumor growth." (PMID 34944738, 2021). "We hypothesized that senescent tumor cells secrete high levels of CXCL12 and form a chemokine gradient from the tumor tissues to the stromal area." (PMID 33643790, 2021). "In addition, the CXCR4/CXCL12 axis has been reckoned as an important marker and mediator of tumor cells homing to bone." (PMID 34712663, 2021). "CXCL12 can also induce the directional migration of tumour cells." (PMID 33803414, 2021). "However, DPP4 displays an antioncogenic function in those tumors linked to the CXCL12/CXCR4 axis, which is known to support neovascularization, tumor growth and metastasis during cancer development." (PMID 33525607, 2021). "The G protein-coupled receptor chemokine (C-X-C motif) receptor 4 (CXCR4) is the membrane receptor for the chemokine CXCL12 and was originally identified in peripheral blood leukocytes and other cell types like hematopoietic stem cells, stromal fibroblasts and tumor cells." (PMID 34440844, 2021). "The chemokine CXCL12 released from tumor cells and CAFs may suppress the infiltration of T lymphocytes through a mechanism called chemorepulsion mediated by CXCR4, which is the receptor for CXCL12 and also expressed on T lymphocytes." (PMID 34293030, 2021). "We found that tipifarnib inhibits CXCL12 expression in pancreatic stellate cells and reduces tumor growth of KRAS WT PDAC in PDX models, suggesting that tipifarnib may benefit a subset of PDAC patients." (PMID 35008248, 2021). "CXCL12 secreted from senescent tumor cells could stimulate fibroblasts by paracrine effect and the activated fibroblast can change the microenvironment around cancer cells by secretion of other chemokines." (PMID 33643790, 2021). "CXCL12 also plays a role to initiate and promote tumor through CXCL12/CXCR4 axis." (PMID 34168096, 2021). "First, we evaluated whether mCXCL12 overexpressing MC38 cells, which mimic the senescent tumor cells secreting CXCL12, could inhibit the effect of ICI by decreasing T cell infiltration." (PMID 33643790, 2021). "Similar to CXCL12, multiple markers of iCAFs were significantly reduced in tumor tissues." (PMID 34801033, 2021). "In this study, we used PDX models of a rare subset of PDAC where the malignant cells are a source of the chemokine where we can test the effect of the FTI in the context of a CXCL12-high PDAC tumor mass, but the role of the T-cell immune response cannot be addressed in these nude mice." (PMID 35008248, 2021). "FGF and CXCL12 released by CAFs are known to induce tumor growth and angiogenesis." (PMID 34946170, 2021). "For example, elevated CXCL12 levels in stroma-rich areas of the tumor mass that lack tumor cell nests could generate a concentration gradient attracting T cells away from the malignant cells themselves." (PMID 35008248, 2021). "To gain more insight into the mobilization of HPCs, we analyzed the expression of genes that regulate HPC maintenance and attraction in the bone marrow (CXCL12, c-kit ligand, angiopoietin-1, vascular cell adhesion molecule-1 and osteopontin) in tumor-bearing mice." (PMID 33603745, 2020). "Also senescent tumor cells produce CXCL12 to promote cancer cell migration and metastasis, and ultimately contributing to tumor development." (PMID 33154552, 2020). "Also, under the stimulation of hypoxia and angiogenic factor, the secretion and aggregation of CXCL12 in the tumor tissues increased." (PMID 32253815, 2020). "Furthermore, the dipeptidyl peptidase (DPP)-4 inhibitor, KR62436, promoted primary tumor growth, and lung metastasis via induction of the CXCL12/CXCR4/mTOR/EMT signaling axis in a syngeneic mouse model." (PMID 32245205, 2020).
tumor (continued). "The CXCR4/CXCL12 interaction is central to tumor cell homing to distant organs." (PMID 32943996, 2020). "Moreover, HMGB1 can increase the release of CXCL12 from stromal cells and induce the aggregation of a large number of neutrophils and dendritic cells (DCs) at the tumor site, thereby eliminating infiltrating tumor cells." (PMID 32551121, 2020). "Moreover, the CXCL12/CXCR4 signaling pathway promotes MDSCs trafficking in the tumor microenvironment." (PMID 33123472, 2020). "Moreover, Plerixafor inhibition of CXCL12/CXCR4 axis can reverse the tumor-promoting signals of stromal cells, increasing the spontaneous apoptosis rate of tumor cells and enhancing their response to chemotherapy." (PMID 32784523, 2020). "CXCL12 attracts both innate and adaptive immune cells into the tumor boosting its growth." (PMID 33096815, 2020). "In addition to CXCL-12, a wide range of CAF-produced chemokines has been associated with tumor immunosuppression." (PMID 33553157, 2020). "We believe that the high expression levels of CXCL12 in these cells immediately surrounding the tumor nests may also abrogate the necessary gradient for triggering migration of tumor cells towards other CXCL12-rich distant locations." (PMID 32758242, 2020). "Moreover, CXCL12 stimulates the expression of α5 and β3 integrins by prostate tumor cells, thereby inducing the adhesion of the tumor cells to human endothelium or extracellular matrix." (PMID 33363463, 2020). "In addition, memory CD8+ T cells fail to elicit the anti-tumor activity in the presence of high levels of CXCL12." (PMID 33096815, 2020). "NK cells have been detected at low levels in the EC microenvironment; this study found significantly high levels of IL-1β and CXCL10 in the tumor, but low levels CXCL12, CCL27, and CCL21 as compared to the surrounding healthy tissue, and the NK cells in EC were compromised in cytotoxicity." (PMID 32226771, 2020). "Thus, we developed an efficient and tunable CXCL12 delivery system as a promising therapeutic strategy that aims to be injected into a hydrogel used to fill the cavity after surgical tumor resection." (PMID 32295255, 2020). "The CXCL12 axis also indirectly exerts anti-apoptotic effects in tumor cells." (PMID 33363463, 2020). "Thus, curcumin and luteolin impair the migratory activity in tumor cells by the repression of the CXCL12/CXCR4 biological axis, as a consequence of the downregulation of MMP-9 by luteolin." (PMID 33195200, 2020). "Its ligand CXCL12 (SDF-1) is highly abundant in tissues that are common sites of metastasis such as lymph nodes, lung or bone, suggesting a specific chemokine-mediated trafficking-pattern of circulating tumor cells." (PMID 33281749, 2020). "This hypothesis was supported by animal studies, showing that CXCR4-positive tumor cells migrated from their primary region to these CXCL12 secreting organs." (PMID 31802362, 2020). "This increase in CXCR4 density in the tumor could be due to treatment-induced increase in the secretion of CXCL12 by stromal cells." (PMID 31802362, 2020). "CXCL12 also functions as a chemoattractant during tumor development." (PMID 33363463, 2020). "Additionally, another study has shown that FAP+ CAFs secrete CXCL12, which coat the tumor cells and block the accumulation of CD8+ T cells to the proximity of the tumor." (PMID 32752017, 2020). "When NOX-A12 is bound to CXCL12 the binding inhibits the development of a CXCL12 gradient in basement membrane stromal cells of the tumor microenvironment, which disrupts tumor proliferation and metastatic ability, and diminishes drug resistance in tumor cells." (PMID 32848740, 2020). "Additionally, IRS1 (insulin receptor substrate 1), DCN (decorin), FMOD (fibromodulin), and CXCL12 (chemokine C-X-C motif ligand 12) were down-regulated in tumor tissues." (PMID 32714651, 2020).
tumor (continued). "In addition, CXCL12 expression was barely detectable in the primary tumor stromal tissue, but was strongly expressed in metastatic lymph node stroma, illustrating the CXCR4/CXCL12 axis as a highly plausible mechanism for metastatic spread in this cancer." (PMID 32296435, 2020). "Immature pDCs also express CXCR4, the receptor for CXCL12, a chemokine produced by tumor cells." (PMID 32486257, 2020). "In addition, tumor-derived CCL2 can directly act on CCR2 positive endothelial cells to increase their permeability or indirectly via increasing CXCL12 expression, which helps CXCR4 positive cancer cells to extravasate into the PMNs." (PMID 33414786, 2020). "Moreover, CXCR4 is highly expressed in the endothelial cells of large vessels in tumor stroma, indicating that the CXCL12/CXCR4 signaling plays a vital role in tumor angiogenesis." (PMID 33363463, 2020). "Furthermore, in ischemic endothelial cells, CXCL12 gene expression in tumor cells is controlled by HIF-1α in direct proportion to reduced oxygen level." (PMID 32456359, 2020). "In the same study, it was shown that rh-CXCL12 and also CXCR4 agonists, pushed MTC cells to enter the G2/M cell cycle phase in a CXCR4-mediated manner and induced the expression of genes associated with EMT and tumor cell invasion." (PMID 32244473, 2020). "Studies have reported that elevated CXCL12 activated multiple signals in tumor cells." (PMID 32381016, 2020). "Immunomodulatory CAFs expressing highly IL-6/CXCL12 identified could activate JAK/STAT signaling in tumor cells, just like iCAFs." (PMID 33292666, 2020). "Of interest, both chemokines were shown to activate fibroblasts, suggesting that CXCL14 and CXCL12 may co-operate in controlling fibroblast functions in various scenarios, including tissue repair, fibrosis and tumor progression." (PMID 33123134, 2020). "In hematological malignancies, as well as in solid tumors, the overexpression of CXCR4 is responsible for metastasis in organs expressing high CXCL12 levels (e.g., lymph nodes and BM), in addition to disease progression, increased tumor cell survival, and chemoresistance." (PMID 32260318, 2020). "CXCL12 can act as a survival factor for tumor infiltrating pDCs." (PMID 32486257, 2020). "Moreover, many reports indicate that binding of CXCL12 to CXCR4 on tumor cells of various types enhances their proliferation, both in vitro and in vivo, either via MAPK or PI3K/Akt pathways." (PMID 32983169, 2020). "Moreover, CXCL12 affects stromal cells and controls transformation of healthy fibroblasts in CAFs, which also release CXCL12 and further fuel tumor growth." (PMID 33096815, 2020). "Plasmacytoid dendritic cells (DCs), which induce neoangiogenesis through production of IL-8 and TNF-α, could be attracted to the tumor environment by CXCL12." (PMID 33363463, 2020). "We identify a critical and previously unappreciated role for MK2-dependent regulation of the well-known pro-angiogenesis factor CXCL-12/SDF-1 secreted by tumor associated-macrophages, in addition to MK2-dependent regulation of Serpin-E1/PAI-1 by several cell types within the tumor microenvironment." (PMID 33708191, 2020). "Ionizing radiation was shown to up-regulate CXCL12/CXCR4 signalling in various tumour entities." (PMID 31959787, 2020). "The enhanced CXCL12 secretion by the hypoxic tumor may lead to the recruitment of CXCR4 expressing bone marrow derived immune cells in order to restore the vasculature of the tumor after radiotherapy." (PMID 31802362, 2020). "In addition, increased expression of CD163+ TAMs and CXCL12 in tumor stroma (TS) and invasive tumor margin (TM) is intimately associated with tumor progression in GC." (PMID 33224886, 2020). "Notably, when mice bearing BC were treated with antibodies targeting CXCL12, reduced tumor volume and cell number were observed." (PMID 32466591, 2020).
tumor (continued). "In addition to TCR signaling pathways, the binding of CXCR4 and chemokine CXCL12 activated several pathways involved in the molecular mechanism of progression, angiogenesis, and metastasis in tumor." (PMID 32640634, 2020). "EVs mainly contained miRNA and proteins, which are known to be metastasis-associated factors such as brain-derived neurotrophic factor (BDNF), C-X-C motif chemokine 12 (CXCL12), and osteopontin, and are potent mediators of communication between tumor cells and stroma." (PMID 32634139, 2020). "CXCR4, which is upregulated during BC progression, interacts with CXCL12 in cancer cells to mediate tumour chemotaxis and invasion through connective tissue, suggesting that CXCR4 may be a potential target for attenuation of BC metastasis." (PMID 32228629, 2020). "Corroborating this observation, preclinical studies in an autochthonous murine model of PDAC revealed that both pharmacological inhibition of CXCR4 and genetic ablation of CXCL12 producing CAFs led to a rapid accumulation of CD8+ T cells within the tumour and reduced tumour growth." (PMID 32967079, 2020). "In addition, it has been shown that the binding of CXCL12 to its receptor enhances the expression of α5 and β3 integrins in PCa cells, two major glycoproteins involved in tumor progression." (PMID 33747899, 2020). "Tumor cells expressing CXCR4 may be attracted toward blood vessels by perivascular fibroblasts that express CXCL12 via synergizing with CXCR4-expressing TAMs." (PMID 32943996, 2020). "CXCL12, a ligand for CXCR4, encodes a protein that acts as a G protein-coupled receptor and is involved in cell processes including immune surveillance, inflammatory responses, and tumor metastasis." (PMID 32235004, 2020). "However, inflammatory conditions and tumor-derived factors (e.g., CXCL12, GM-CSF, and CCL2) induce the activation and accumulation of MDSC in SLOs." (PMID 33343570, 2020). "Such increased CXCL12 expression was an unfavorable predictor of tumor progression in LGGs." (PMID 32456359, 2020). "HSF1 promotes tumor growth by inducing cytokines such as CXCL12 and TGF-β." (PMID 32546182, 2020). "CXCL12 used “Exon 5′’ to a greater extent in tumor samples, whereas CXCL12 only containing exons 1–3 was expressed much lowly in normal samples, which means that CXCL12 AT Exon 5 could increase the expression of NP_001029058.1." (PMID 32849842, 2020). "Furthermore, CXCL12/CXCR4 axis supports fibrotic tumor microenvironment and prevents therapeutic effects of immune checkpoint blockers." (PMID 33096815, 2020). "mAbs, such as BMS-936564/MDX-1338 and LY2624587, could also suppress CXCR4/CXCL12 signaling pathways and inhibit tumor growth and metastasis in different animal models both in vitro and in vivo." (PMID 33392074, 2020). "Furthermore, iCAFs have been widely proved to promote tumor progression by secreting chemokines and cytokines such as IL-6 and CXCL12." (PMID 33292666, 2020). "On the contrary, there is other evidence that CXCL12 protein was frequently expressed in normal tissues (56.7%), in para-cancerous diseases tissues (46.7%), and in pancreas surrounding lymph nodes (50%); instead, only 13.3% of tumor tissues expressed it." (PMID 31275385, 2019). "Interestingly, we further found that the frequency of mast cells was positively correlated with CXCL12 production, which most likely derived from EpCam+ tumor cells in the GC microenvironment." (PMID 30808413, 2019). "MDSCs normally circulate in the bloodstream and are drawn to areas of inflammation and ischemia through chemokine molecules such as CXCL12 produced by fibroblasts, as well as growth factors such as granulocyte–macrophage colony stimulating factor (GM-CSF) from tumor cells in PDA." (PMID 30931508, 2019). "We observed a significant decreased volume and a higher number of cells required to generate tumor sphere in shNotch1 group while the additional 100 ng/ml of CXCL12 could significantly rescue this trend and boost the self-renewal ability of GICs." (PMID 31382985, 2019).
tumor (continued). "Activation of CXCR4 by CXCL12 has been reported to have pro-tumor activity." (PMID 30873179, 2019). "The importance of BMs is also suggested by in vitro studies, which underline that NEN cells exhibit osteotropism and that the mechanisms involved in the formation of BMs, including the EMT and the alteration of RANKL/OPG and CXCR4/CXCL12 pathway, are similar to those found in other tumor types." (PMID 31500357, 2019). "In cancer, the binding between CXCL12 and its receptors causes different pathways activation, that, through cancer cells, migration, angiogenesis, and epithelial to mesenchymal transition (EMT), are involved in tumor initiation and progression." (PMID 31275385, 2019). "CXCL12 signaling via CXCR4 is critical for the regulation of hematologic tumor cell adhesion." (PMID 30787933, 2019). "ACKR3 may provide an advantage for tumor cells that favors their metastasis, driving cells through CXCL12 gradients by binding and degrading CXCL12–regulating bioavailability and gradient control, as it does during development." (PMID 30800123, 2019). "Besides, several chemokines including CXCL9, CXCL10, and CXCL12 were upregulated by genome-wide transcriptional profiling of tumor-infiltrated PTL-CAR-T cells." (PMID 31511513, 2019). "In particular, CXCL12 is mainly released by CAFs, which represent the 50% of tumor stroma." (PMID 31275385, 2019). "Moreover, α-SMA+ CAFs in HCC attract monocytes to the tumor stroma by the secretion of CXCL12 and facilitate their differentiation into MDSCs in a IL-6-STAT3-dependent manner, thus contributing to the suppression of adaptive immune responses." (PMID 31462327, 2019). "Stromal cells surrounding primary tumours or metastatic lesions may secrete high levels of CXCL12/SDF1 and induce CXCR4 expression in tumour cells supporting the hypothesis that CXCR4 is important for tumour growth." (PMID 31877673, 2019). "TGF-β and CXCL12 appear to modulate the relative populations of tumor infiltrating lymphocytes and their respective activities; this has been demonstrated by studies showing the blockade of TGF-β or CXCL12 to potentiate tumor responses to immune checkpoint blockades across multiple tumor models." (PMID 31514477, 2019). "In addition, TCF12 participates in the angiogenesis of endothelial cells in the tumor microenvironment via regulation of CXCL12 and CXCR4-mediated bFGF expression." (PMID 31534521, 2019). "Interestingly, studies have reported that CD9 and CXCL12 are associated in a CD9/CXCL12/CXCR4 signaling pathway, and activation of this pathway is linked to increased tumor invasion, metastasis, and chemoresistance." (PMID 31191817, 2019). "Thus, besides decreasing CXCR4 expression and altering CLL cell trafficking, ibrutinib, and SEL24-B489 also inhibited CXCL12/CXCR4-mediated CLL cell-tumor microenvironment cross-talk signaling, such as induction of cell survival and CD20 upregulation." (PMID 30787933, 2019). "Additionally, a tumor-associated inflammatory mediator, prostaglandin E2 (PGE2), has demonstrated a role in controlling the expression and interactions of CXCL12 and its respective receptor, CXCR4, which are implicated in the process of tumor progression." (PMID 31354741, 2019). "Moreover, CXCR4, with its ligand CXCL12, played a critical role in tumor progression induced by TCF12 via activation of the MAPK/ERK and PI3K/AKT signaling pathways." (PMID 31534521, 2019). "However, since some molecular differences among CXCL12 isoforms exist, once the specific functions of each isoform in tumor development and progression are clarified, it will be necessary to design CXCL12 isoform-specific therapies." (PMID 31275385, 2019). "MDSC are recruited toward PaCa via CAF-derived CXCL12 and tumor-derived GM-CSF." (PMID 31921628, 2019). "Therefore, CXCL12/CXCR4/PI3K/Akt signaling pathway has become a hot topic in tumor research and also provides a specifc target spot for cancer treatment." (PMID 31500630, 2019).